TRMT13 (tRNA methyltransferase 13)
Description:
tRNA methylase which 2'-O-methylates cytidine(4) in tRNA(Pro) and tRNA(Gly)(GCC), and adenosine(4) in tRNA(His).
Synonyms: CCDC76; FLJ10287; FLJ11219; hTrmt13
Tractability: Antibody: the Human Protein Atlas places it where antibodies can reach. PROTAC: ubiquitination databases record sites on it.
Gene: Protein-coding gene on chromosome 1 (100,133,045 to 100,150,496, forward strand). Ensembl gene ENSG00000122435.
Subcellular location (Human Protein Atlas): Nucleoplasm; Plasma membrane; Cytosol; Nuclear bodies
Pathways (Reactome):
Metabolism of RNA: tRNA modification in the nucleus and cytosol
Gene Ontology:
Molecular function: protein binding; tRNA methyltransferase activity; methyltransferase activity
Biological process: tRNA methylation; tRNA processing
Genetic constraint (gnomAD): Loss-of-function variants: 36 observed, 45.42 expected, observed/expected ratio (o/e) 0.79, 90% interval 0.61 to 1.05. The upper end of that interval is the gene's LOEUF score, 1.05, which puts it in group 4 of 6, group 1 being the genes least tolerant of losing a copy. Missense variants: 461 observed, 528.52 expected, observed/expected ratio (o/e) 0.87, 90% interval 0.81 to 0.94. Synonymous variants: 165 observed, 190.62 expected, observed/expected ratio (o/e) 0.87, 90% interval 0.76 to 0.99.
Homologues: Orthologues: chimpanzee TRMT13 (99% identical), macaque TRMT13 (98% identical), rabbit TRMT13 (91% identical), dog TRMT13 (91% identical), pig TRMT13 (91% identical), guinea pig TRMT13 (89% identical), rat Trmt13 (85% identical), mouse Trmt13 (85% identical), zebrafish trmt13 (55% identical), tropical clawed frog trmt13 (53% identical), Drosophila melanogaster CG18048 (29% identical), Caenorhabditis elegans Y49A3A.3 (23% identical).
Diseases named in the same sentence as TRMT13 in open-access papers:
TRMT13 is named in the same sentence as 5 diseases in open-access papers, as found by Europe PMC text mining. Sharing a sentence is not in itself a finding about the gene and the disease. The quoted sentences say what the papers report.
Tumor (2 papers, 2017 to 2024). "We created tumor-bearing nude mouse models from the control, TRMT13+/+, lentiviral NC, TRMT13 siRNA, and siRNA NC groups to investigate the impact ofTRMT13 on PTC progressionin vivo." (PMID 38425244, 2024). "However,TRMT13 overexpression significantly reduced tumor volume, whereasTRMT13 silencing significantly promoted tumor growth and reduced survival." (PMID 38425244, 2024). "A nude mouse tumor model is used to evaluate the effects of TRMT13 and ANAPC4 on PTC tumorigenesis." (PMID 38425244, 2024). "Here, bioinformatics analyses revealed that TRMT13 is downregulated in PTC and that its expression is inversely correlated with cancer cell growth/tumor progression." (PMID 38425244, 2024). "Tumor volume and mass were greater in the TRMT13+/++ANAPC4 siRNA group than in the TRMT13+/+ group and lower in the TRMT13 siRNA+ANAPC4+/+ group than in the TRMT13 siRNA group." (PMID 38425244, 2024). "The relative TRMT13 and ANAPC4 expression levels in the tumor tissue are shown inFigure 8D,E." (PMID 38425244, 2024).
cancer (1 paper, 2024). A tumor composed of atypical neoplastic, often pleomorphic cells that invade other tissues. "ROC analyses indicated that TRMT13 expression significantly influenced patient cancer diagnosis." (PMID 38425244, 2024). "Compared with those in the control group, cancer cell migration and invasion were lower in the TRMT13+/+ and ANAPC4+/+ groups but greater in the TRMT13 siRNA and ANAPC4 siRNA groups." (PMID 38425244, 2024). "Subsequent analyses confirm that both TRMT13 and ANAPC4 expressions are downregulated in PTC tissues and that this change in expression has a significant impact on cancer diagnosis." (PMID 38425244, 2024).
TRMT13 also shares sentences with these, for which no sentence is quoted: cervical cancer (1 paper); lung carcinoma (1); papillary thyroid cancer (1).